BCAS3 (BCAS3 microtubule associated cell migration factor)
Description:
Plays a role in angiogenesis. Participates in the regulation of cell polarity and directional endothelial cell migration by mediating both the activation and recruitment of CDC42 and the reorganization of the actin cytoskeleton at the cell leading edge. Promotes filipodia formation (By similarity). Functions synergistically with PELP1 as a transcriptional coactivator of estrogen receptor-responsive genes. Stimulates histone acetyltransferase activity. Binds to chromatin. Plays a regulatory role in autophagic activity. In complex with PHAF1, associates with the preautophagosomal structure during both non-selective and selective autophagy. Probably binds phosphatidylinositol 3-phosphate (PtdIns3P) which would mediate the recruitment preautophagosomal structures.
Synonyms: FLJ20128; PHAF2; GAOB1; HEMARS; MAAB
Tractability: PROTAC: UniProt records ubiquitination sites on it; ubiquitination databases record sites on it; its protein half-life has been measured.
Gene: Protein-coding gene on chromosome 17 (60,677,453 to 61,392,838, forward strand). Ensembl gene ENSG00000141376.
Subcellular location: Nucleus; Cytoplasm; Cytoplasm, cytoskeleton; Preautophagosomal structure
Subcellular location (Human Protein Atlas): Nucleoli
Gene Ontology:
Molecular function: acetyltransferase activator activity; beta-tubulin binding; chromatin binding; histone acetyltransferase binding; histone binding; nuclear receptor binding; phosphatidylinositol binding; protein binding; enzyme activator activity
Biological process: cellular response to estrogen stimulus; positive regulation of catalytic activity; positive regulation of transcription by RNA polymerase II; response to estrogen; cell-cell signaling; positive regulation of endothelial cell migration; regulation of actin cytoskeleton organization; autophagy
Cellular component: cytoplasm; euchromatin; nucleus; phagophore assembly site; cell leading edge; cytoplasmic microtubule; intermediate filament cytoskeleton; cytoskeleton
Genetic constraint (gnomAD): Loss-of-function variants: 39 observed, 87.81 expected, observed/expected ratio (o/e) 0.44, 90% interval 0.34 to 0.58. The upper end of that interval is the gene's LOEUF score, 0.58, which puts it in group 2 of 6, group 1 being the genes least tolerant of losing a copy. Missense variants: 762 observed, 1,008.7 expected, observed/expected ratio (o/e) 0.76, 90% interval 0.71 to 0.8. Synonymous variants: 347 observed, 366.46 expected, observed/expected ratio (o/e) 0.95, 90% interval 0.87 to 1.03.
Homologues: Orthologues: macaque BCAS3 (99% identical), chimpanzee BCAS3 (99% identical), dog BCAS3 (99% identical), pig BCAS3 (98% identical), mouse Bcas3 (97% identical), rabbit BCAS3 (96% identical), rat Bcas3 (93% identical), guinea pig BCAS3 (93% identical), tropical clawed frog bcas3 (88% identical), zebrafish bcas3 (85% identical), Drosophila melanogaster rudhira (41% identical), Caenorhabditis elegans F56C9.10 (27% identical).
Diseases named in the same sentence as BCAS3 in open-access papers:
BCAS3 is named in the same sentence as 41 diseases in open-access papers, as found by Europe PMC text mining. Sharing a sentence is not in itself a finding about the gene and the disease. The quoted sentences say what the papers report.
breast carcinoma (26 papers, 2007 to 2023). "Of these genes, only RPS6KB1, VMP1, PPM1D and BCAS3 have been implicated in tumor development using clinical data from breast cancer patients." (PMID 34797887, 2021). "BCAS3 is a coactivator of estrogen receptor alpha (ER-α) and is overexpressed in breast cancer cells, in which it is associated with tumor grade and proliferation." (PMID 29879923, 2018). "BCAS3 is overexpressed and associated with impaired response to tamoxifen in ER positive premenopausal breast cancers." (PMID 24019942, 2013). "Regarding the association of CHEK2 with breast cancer, it is of interest that also one borderline significant SNP is located in a gene breast carcinoma amplified sequence 3 (BCAS3) involved in this pathway." (PMID 20548946, 2010). "However, the members of the RrATG18 subfamily were still divided into two groups because the special breast carcinoma amplified sequence 3 (BCAS3) was only encoded by RrATG18g and RrATG18h." (PMID 36979491, 2023). "BCAS4 is either amplified, overexpressed or fused with the last two exons of BCAS3 to BCAS4 in breast cancer." (PMID 37019990, 2023). "BCAS3 is expressed in tumor-derived cell lines such as HeLa and MCF-7, is amplified in 9% of initial breast tumors, and is linked to breast cancer progression." (PMID 38259392, 2023). "The breast carcinoma amplified sequence (BCAS3), initially identified as amplified and overexpressed in breast cancer, shares 98% identity with murine Rudhira." (PMID 38259392, 2023). "We then detected BCAS3 amplification frequency in six breast cancer cohorts and found that the most frequent BCAS3 alteration was amplification." (PMID 34240781, 2021). "BCAS3 (Breast cancer‐amplified sequence 3), 98% identical to murine Rudhira, was originally identified to be amplified and overexpressed in breast cancer." (PMID 34240781, 2021). "Compared with normal samples, we found that BCAS3 expression was remarkably elevated in breast cancer tissues." (PMID 34240781, 2021). "DDB_G0272949 is homologous to BCAS3, a gene upregulated in breast cancer and other malignancies, which is essential for angiogenesis and survival of mouse embryos, where BCAS3 localizes to microtubules and intermediate filaments." (PMID 32116088, 2021). "The results revealed that the BCAS3 amplification frequency was higher in breast cancer than the other four tissue‐derived tumours." (PMID 34240781, 2021). "High BCAS3 expression promoted growth, inhibited apoptosis and conferred chemoresistance in breast cancer cells." (PMID 34240781, 2021). "Next, we explored the protein level of BCAS3 in human breast carcinoma tissues using IHC staining in 140 cases of breast tumour tissues, and the results indicated an increased level of BCAS3 in tumours compared with normal tissues." (PMID 34240781, 2021). "The functional characterization of BCAS3 offers new insights into the oncogenic properties and chemotherapy resistance in breast cancer." (PMID 34240781, 2021). "Breast cancer‐amplified sequence 3 (BCAS3) was initially found to be amplified in human breast cancer (BRCA); however, there has been little consensus on the functions of BCAS3 in breast tumours." (PMID 34240781, 2021).
breast carcinoma (continued). "The top two signal SNPs (rs11653176 and rs9905274) are localized in the intron of BCAS3 (breast carcinoma amplified sequence 3)." (PMID 25967671, 2015). "BCAS4 and BCAS3 are located at 20q13 and 17q23, respectively, regions which undergo amplification, overexpression and fusion in breast cancers." (PMID 26040699, 2015). "We have taken advantage of this system to analyze the developmental and pathological expression of BCAS3 a gene known to be important in breast cancer." (PMID 18030336, 2007). "Expression of BCAS3 mRNA in medulloblastoma of cerebellum and BCAS3 protein in breast cancer has been reported." (PMID 18030336, 2007). "BCAS3 expression is driven by estrogen-positive breast cancer cells." (PMID 38259392, 2023). "High BCAS3 expression and ER/PR positivity hinder tamoxifen response in breast cancer patients." (PMID 38259392, 2023). "In particular, primary breast cancers demonstrate an amplification rate of 9.4% for the BCAS3 gene." (PMID 38259392, 2023). "The BCAS3 gene stands out as a promising biomarker for breast cancer." (PMID 38259392, 2023). "Further, BCAS3 may be a novel predictor for prognosis and guide chemotherapy regimens for patients with breast cancer." (PMID 34240781, 2021). "Also MTA1, a known corepressor for ERɑ, was shown to function as a coactivator for the gene BCAS3 that was described to be overexpressed and amplified in breast cancer." (PMID 29312638, 2017). "Two palindrome candidates, 17q23.2 (Chr17: 56,691,822-56,700,625) and 20q13.2 (Chr20: 52,771,235-52,783,881), contained the BCAS3 and ZNF217 genes that was amplified and overexpressed in breast cancers and was often associated with chromosomal alterations affecting the locus." (PMID 24885769, 2014). "However BCAS3 is amplified in 9% of primary breast tumors, is expressed in tumor-derived cell lines like HeLa and MCF-7 and is implicated in breast cancer progression." (PMID 18030336, 2007). "The normal expression pattern of BCAS3 has not been studied, though it is implicated in breast cancer progression." (PMID 18030336, 2007). "Genetically, BCAS3 is fused with BCAS4 and is located on human chromosome 17q23, a region harboring several oncogenes with approximately 20% amplification in primary breast carcinomas." (PMID 38259392, 2023). "As expected, the top enriched pathways are genes in amplified regions previously identified from breast cancer, such as genes like ZNF217 and BCAS3 in MCF7; a selected list of luminal genes have also been enriched in the luminal cell lines MCF7 and T47D." (PMID 36153537, 2022). "The facts that fusion reads spanned the fusion boundary between the BCAS4 and BCAS3 genes on chromosomes 20 and 17 proved that BCAS4 and BCAS3 gene fused and expressed in the MCF7 breast cancer cell line." (PMID 28761119, 2017). "As the MCF‐7 cell line belongs to the ER + breast cancer subtype based on data from the ATCC, we determined whether BCAS3 affected chemoresistance." (PMID 34240781, 2021). "Finally, only 1 (BCAS4/BCAS3), 1 (BSG/NFIX), 2 (STX16/RAE1, RAB22A/MYO9B) and 0 fusions have been reported by all the tools within the considered breast cancer cell lines." (PMID 28114882, 2017).
breast carcinoma (continued). "For example, the fusion BCAS3-BCAS4 (breast carcinoma amplified sequence 3/4), whose partner gene BCAS3 and BCAS4 were both widely known as overexpression sequence and fusion in breast cancer, detected in MCF-7 cell line was nominated as top one fusion driver by RWCFusion." (PMID 27506935, 2016). "BCAS3-BCAS4 gene fusion, which has previously been reported in breast carcinomas, was validated as the product of a fusion gene between BCAS4 and BCAS3, which resulted from amplification followed by a translocation event between the two loci chr20q13 and chr17q2372." (PMID 26113264, 2015). "Several of the fused genes are also recurrently broken in a substantial proportion of breast cancers, as judged by copy number steps in array-CGH of 1000 breast tumours: around 10% have breaks in ERBB2, BCAS3 and SKAP1, while COL14A1, TIAM1, USP32, TAOK1 are broken in around 4%." (PMID 23260012, 2012). "For example, PHF20L1, BCAS3, TAOK1, PCGF2, and TRPS1 are fused in other breast cancers." (PMID 23260012, 2012). "Several of the genes involved are also in signalling pathways relevant to breast cancer: ERBB2, NRIP1 and BCAS3 are involved in estrogen receptor function and APPBP2 with androgen receptor; while TAOK1 and SKAP1 are involved in MAPK signalling and DEPDC6/DEPTOR regulates mTOR signalling." (PMID 23260012, 2012). "However, the function of BCAS3 in breast cancer has not yet been defined and needs to be explored experimentally." (PMID 34240781, 2021).
gout (11 papers, 2015 to 2022). A condition characterized by painful swelling of the joints, which is caused by deposition of urate crystals. "Rs11653176 in BCAS3 is significantly associated with uric acid levels and gout in Japanese and Chinese Han populations." (PMID 35813212, 2022). "BCAS3 polymorphisms were previously associated via GWAS with gout, traits of kidney disease, and coronary artery disease." (PMID 34070617, 2021). "We genotyped the variants of RFX3 (rs12236871), KCNQ1 (rs179785) and BCAS3 (rs11653176) in 723 Japanese clinically defined gout cases and 913 controls by TaqMan method." (PMID 29879923, 2018). "The common variant of BCAS3, rs11653176, showed a significant association with gout (P = 1.66 × 10− 3; odds ratio [OR] = 0.80; 95% confidence interval [CI]: 0.70–0.92)." (PMID 29879923, 2018). "Our present replication study, as did the previous gout GWAS, demonstrated the common variant of BCAS3 to be associated with gout susceptibility." (PMID 29879923, 2018). "rs11653176, a common variant of BCAS3, showed a significant association with gout (P = 1.66 × 10− 3; odds ratio [OR] = 0.80); the direction of effect was the same as that seen in the previous Han Chinese GWAS." (PMID 29879923, 2018). "Three BCAS3 SNPs, rs9895661, rs9905274, rs11653176, were associated with gout in Han Chinese male populations." (PMID 30123371, 2018). "In this study, we were able, for the first time, to replicate the association between rs11653176 of BCAS3 and gout." (PMID 29879923, 2018). "As expected, most of the urate loci are also risk factors for gout, with only four loci (INHBB, HNF4G, UBE2Q2, and BCAS3) yet to be formally associated with gout at a nominal level of significance." (PMID 25889045, 2015). "BCAS3 was identified here for the first time by the GWAS approach with Japanese individuals, while Li et al18 reported that rs11653176, another SNP of BCAS3, is associated with gout based on a GWAS with a Han Chinese population." (PMID 32238385, 2020). "Thus, although additional genetic and/or functional analyses will be necessary, the common variant of BCAS3 might affect gout susceptibility in ways that are attributable to individual differences in responses to the effects of estrogen." (PMID 29879923, 2018). "Together with these gout loci, BCAS3, which is originally identified by the Chinese gout GWAS, will be very important for personalized genome medicine and/or prevention of gout." (PMID 29879923, 2018). "A recent genome-wide association study (GWAS) of gout identified three new loci for gout in Han Chinese: regulatory factor X3 (RFX3), potassium voltage-gated channel subfamily Q member 1 (KCNQ1), and breast carcinoma amplified sequence 3 (BCAS3)." (PMID 29879923, 2018). "And 11 of the significant variants were from the gout associated loci (GCKR, SLC2A9, ABCG2, CNIH2, MYL2-CUX2 (ALDH2) and BCAS3)." (PMID 28642574, 2017). "Our findings suggest that risk allele (C) of rs11653176 of BCAS3, may increase renal urate reabsorption which results in increase of SUA levels and gout risk." (PMID 29879923, 2018). "Thus we included the BCAS3 region as novel loci for gout here." (PMID 25967671, 2015). "The Chinese GWAS used hyperuricaemic controls in follow-up testing to demonstrate that the newly discovered loci (BCAS3, RFX3 and KCNQ1) are likely to be involved in pathways leading to presentation with gout in people with hyperuricaemia." (PMID 28566086, 2017).
breast tumors (4 papers, 2007 to 2021). "It has been reported that BCAS3 excessive expression in premenopausal breast tumours seems to weaken the therapeutic effect of tamoxifen." (PMID 34240781, 2021). "This reflects the heterogeneity in the neoplastic cell population of brain tumors and a probable role of BCAS3 in tumor progression as seen in the breast tumors." (PMID 18030336, 2007). "BCAS3 was found to have an amplification rate of 9.4% in primary breast tumours." (PMID 34240781, 2021).
brain tumors (3 papers, 2007 to 2023). "We also amplified BCAS3 from cDNA of various glioma cell lines that represent malignant human brain tumor cells." (PMID 18030336, 2007). "Having established the expression of BCAS3 in glioma cell lines in vitro, we looked for similar expression in brain tumor tissue and wall of brain abscess rich in vasculature." (PMID 18030336, 2007). "We suggest that BCAS3 is mis-expressed in brain tumors and could serve as a human ES cell and tumor marker." (PMID 18030336, 2007). "In brain tumors such as glioblastoma, hemangiopericytoma, and brain abscess, the observed elevated BCAS3 expression was not only within tumor cells but also the expression of the BCAS3 gene in vascular precursors derived from human ES cells has a role in the formation of tumor vessels." (PMID 38259392, 2023). "We also find that most samples expressing BCAS3 are grade III and IV brain tumors though not all high-grade samples showed expression." (PMID 18030336, 2007).
glioblastoma (3 papers, 2007 to 2023). The most malignant astrocytic tumor (WHO grade IV). "These outcomes align with prior research identifying BCAS3 as a prognostically significant biomarker in diverse malignancies such as breast and glioblastoma." (PMID 38259392, 2023). "BCAS3 is expressed in the neo-angiogenic component of glioblastoma, hemangiopericytoma and brain abcess wall." (PMID 18030336, 2007). "Eight samples showed strong immunoreactivity for BCAS3; over 50% of the cells being BCAS3+ (five glioblastomas, two hemangiopericytomas and one abscess)." (PMID 18030336, 2007). "We found a large number of BCAS3- expressing cells in different types of brain lesions including glioblastoma, hemangiopericytoma and wall of an abscess." (PMID 18030336, 2007). "In glioblastoma, hemangiopericytoma and brain abscess we note high levels of BCAS3 expression in tumor cells and some blood vessels." (PMID 18030336, 2007). "Their research revealed substantial overexpression of BCAS3 in glioblastoma multiforme (GBM), correlating with an unfavorable prognosis." (PMID 38259392, 2023).
hemangiopericytoma (3 papers, 2007 to 2023). An antiquated term that refers to benign or malignant mesenchymal neoplasms characterized by the presence of neoplastic spindle-shaped to round cells arranged around thin-walled branching vascular spaces. "We report that the protein encoded by BCAS3 is mis-expressed in brain neo plastic and reparative lesions like glioma, abscess and hemangiopericytoma." (PMID 18030336, 2007). "We also show that BCAS3 is mis-expressed in different types of brain lesions that include a malignant glial tumor, a highly mitotic vascular tumor arising from meninges (hemangiopericytoma) and the newly formed channels in the wall of brain abcess." (PMID 18030336, 2007).
coronary artery disease (2 papers, 2018 to 2021). "Rudhira/Breast Carcinoma Amplified Sequence 3 (BCAS3) is a cytoskeletal protein that promotes directional cell migration and angiogenesis in vitro and is implicated in human carcinomas and coronary artery disease." (PMID 29618843, 2018).